NOX4 (NADPH oxidase 4)
Diseases named in the same sentence as NOX4 in open-access papers (continued):
Sharing a sentence is not in itself a finding about the gene and the disease.
kidney disease (45 papers, 2011 to 2025). "As a major source of reactive oxygen species (ROS), overactivation of NOX4 is closely associated with tissue damage and fibrosis in kidney disease." (PMID 39720588, 2024). "In addition, NADPH oxidases (NOX2 and NOX4) are a family of enzymes that catalyze the generation of ROS, and have been linked with the development of kidney disease." (PMID 32153399, 2020). "Our findings support this association, as PEP 2-8 treatment reduced protein tyrosine nitration and downregulated NOX4—a key member of the NADPH oxidase family implicated in mitochondrial oxidative stress and the pathogenesis of various renal diseases." (PMID 41009504, 2025). "The available evidence indicates that the role of NOX4 markedly fluctuates depending on the specific type and stage of renal disease." (PMID 41154471, 2025). "In renal diseases, H2S exhibits remarkable antioxidant and anti-inflammatory effects and effectively inhibits NOX4-induced oxidative stress." (PMID 39720588, 2024). "Previous studies, along with ours, have shown that inhibiting HuR significantly reduces NF-kB signaling, nucleotide-binding oligomerization domain 2 (NOD2) or IL-17-mediated inflammation, and Nox2- or Nox4-mediated oxidative stress in kidney diseases." (PMID 39273597, 2024). "NOX4 is a primary source of ROS in the kidney and plays an important role in various kidney disorders." (PMID 37754228, 2023). "As a major contributor of ROS in the kidney, NOX4 is a promising potential therapeutic candidate for protection against oxidative stress injury in kidney disease." (PMID 37284448, 2023). "NOX4 is an enzyme that plays a critical role in ROS production and oxidative stress in renal diseases." (PMID 36985731, 2023). "The present study aimed to investigate the potential of Nox4 as a therapeutic target for AOPPs-RSA-induced kidney disease by examining its role in the pathogenesis of AOPPs-RSA." (PMID 37049779, 2023). "Considering the link between SH3YL1 and NOX4, it is necessary to confirm the significance of this biomarker in kidney diseases, in addition to detecting its level in various tissues, including the kidney." (PMID 37109492, 2023). "It is well known that PKC, phosphoinositide 3-kinase, ERK, mothers against decapentaplegic homolog, and AMP-activated protein kinase pathways are important for the activation of NOX4 in various kidney diseases." (PMID 36358467, 2022). "The finding that renal disease reduces Nox4 expression has, meanwhile, been recapitulated by others and suggests that Nox4 is a marker for healthy, differentiated, intact renal tissue." (PMID 34356336, 2021). "Compared with other NOXs subtypes, NOX4 plays a more influential role in the pathogenesis of kidney disease." (PMID 33071778, 2020). "It has been shown that NOX4 is a major source of ROS in the kidney and plays a critical role in kidney diseases including cisplatin-induced AKI." (PMID 33291262, 2020). "Current evidence suggests that NOX4 mainly contributes to ROS production and oxidative stress in various kidney diseases, including AKI." (PMID 33287398, 2020). "Further investigation is still required to assess this effect of OMG and this would be of potential importance because pharmacological inhibition of Nox4 has received massive consideration as a therapeutic strategy for many kidney diseases." (PMID 33180794, 2020). "Because of the close relationship between NOX4 and oxidative stress-induced kidney diseases, we measured the mRNA and protein of NOX4." (PMID 30151074, 2018). "Although NOX1 can also be detected in renal cells, including glomerular endothelial cells, podocytes, and tubulointerstitial cells, the dominant NOX isoform in the kidney and the primary source of reactive oxygen species (ROS) in renal disease is widely recognized as NOX4." (PMID 41154471, 2025).
kidney disease (continued). "Emerging evidence implicates nicotinamide adenine dinucleotide phosphate (NADPH) oxidase 4 (NOX4) in the pathological processes of various kidney diseases, but its role in RIAKI remains unclear." (PMID 41154471, 2025). "The progression of kidney disease is accelerated by Ang II and NOX4-induced renal cell death." (PMID 37841924, 2023). "Evidence shows that Nox4 interplays with HIF1α and plays a critical role in various renal diseases." (PMID 35966094, 2022). "Additionally, it should be recognized that Nox4 protects against vascular inflammation and oxidative stress as well as kidney disease, although the mechanisms involved in those protective effects of Nox4 are not clear." (PMID 29088780, 2017). "Other studies invalidated the theory stating that Nox4 is solely a major driver of renal disease; it was shown that, under particular conditions, Nox4 may limit injury and disease progression." (PMID 26491232, 2015). "This view is corroborated by a recent study of the role of NOX4 in murine models of kidney disease." (PMID 24466344, 2014). "Despite numerous publications, there is currently no consensus regarding the role of Nox4 in renal disease, as interpretations vary according to the loss of function strategy (inhibitor, knockdown, knockout, dominant negative enzyme) or model system (cell culture, mouse model, rat model)." (PMID 34356336, 2021). "In conclusion, GL-PP has the potential to treat DOX-induced kidney disorders by reducing inflammation and fibrosis by inhibiting PRR, regulating RAS and NOX4, and lowering the production of inflammatory fibrotic factors." (PMID 37841924, 2023). "NOX4 is the most distributed NOX isoform in the kidney and has been studied in various kidney diseases." (PMID 32967113, 2020). "Notably, NOX4, which generates H2O2 and contributes to various renal diseases, is prominently expressed in the kidney." (PMID 37841924, 2023).
cardiovascular diseases (40 papers, 2012 to 2025). "The potential risk of cardiovascular disease should be considered when using NOX4 inhibitors." (PMID 36407440, 2022). "These include the interaction of multiple cell types that express Nox4, differences between the various Nox4 knockout mice, developmental compensation for the loss of Nox4, a paucity of reliable inhibitors and the suitability of the mouse as a model of cardiovascular disease." (PMID 23125837, 2012). "Like the goddess Nox who embodies both creation and destruction, NOX4 plays a crucial role in various biological processes, yet its activity can also lead to oxidative stress and cellular damage, contributing to cardiovascular diseases." (PMID 41009041, 2025). "Given its broad roles in both cardiac and vascular physiology, NOX4 represents a promising therapeutic target for enhancing myocardial resilience and promoting repair in cardiovascular disease." (PMID 41009041, 2025). "NOX4 is one of the seven members of the Nox family and has been recognized as a prospective target for cardiovascular disease in recent years." (PMID 39598345, 2024). "Setanaxib (GKT137831), a preferential direct inhibitor of NOX1 and NOX4, can delay or prevent the progression of many cardiovascular disorders by inhibiting reactive oxygen species (ROS) generation." (PMID 35444554, 2022). "NOX4 attenuates age-related mitochondrial oxidative stress and vascular inflammation and reduces the incidence of cardiovascular disease." (PMID 36407440, 2022). "In cardiovascular diseases, an increase of NRF2 and NOX4 transcripts has been associated with protective activities against cell death and tissue damage." (PMID 36567907, 2022). "Overexpression of NOX4 has been observed in several pulmonary and cardiovascular diseases, including AS, pulmonary hypertension, and pulmonary fibrosis." (PMID 33744854, 2021). "Elevated NOX4 expression and activity have been reported in a number of renal and cardiovascular diseases, including HTN." (PMID 32183375, 2020). "Evidence supports the view that NOX4 plays a crucial role in many cardiovascular diseases, especially in the pathogenesis of HPH." (PMID 32587469, 2020). "This possible beneficial effect of NOX4 in CH-induced PH is consistent with previous investigations showing the protective role of NOX4 in cardiovascular diseases." (PMID 33076504, 2020). "Basal NOX4-derived H2O2 appears to have some vascular-protective effects, while increased NOX4 expression can exert both adverse and protective actions in cardiovascular disease models." (PMID 31387997, 2019). "While Nox1, Nox2, and Nox4 have been well characterized in models of cardiovascular disease, little is known about Nox5." (PMID 30334629, 2019). "NOX-4 mediates cardiovascular disease in hyperlipidemic mice and expression of NOX-4 in wall of the human artery is related with atherosclerotic severity." (PMID 28878685, 2017). "NADPH oxidase 4 (Nox4) as a major source of oxidative stress in the heart offers a new therapeutic target in cardiovascular disease." (PMID 28230797, 2017). "There is additionally evidence that Nox4 contributes to oxidative stress in cardiovascular diseases." (PMID 26622496, 2015). "NOX4 has been shown to play a crucial role in the pathophysiology of cardiovascular diseases, diabetic complications and fibrosis." (PMID 24317376, 2014). "The literature describes a pathophysiological role for Nox4 in cardiovascular disease; however, some studies have reported that it has a protective role." (PMID 23606947, 2013). "Changes in Nox4 mRNA and protein expression and the effect of targeting Nox4 on cardiovascular diseases." (PMID 23125837, 2012). "The following subsections will outline current knowledge of the role of Nox4 in various cardiovascular diseases." (PMID 23125837, 2012).
cardiovascular diseases (continued). "The goal of this review is to summarize the recent literature on the genetic and enzymatic regulation, subcellular localization, signaling pathways, and the role of Nox4 in cardiovascular disease states." (PMID 23125837, 2012). "In conclusion, NOX4 is a dual-function enzyme that can both exacerbate and protect against cardiac pathology, making it a promising, though complex, therapeutic target for various cardiovascular diseases." (PMID 41009041, 2025). "The results showed TFDM was the main active ingredient in DML and could exert therapeutic effects on cardiovascular diseases through the NOX-4/ROS/p38 MAPK, Bcl-2/Bax and AMPK/SIRT1/PGC-1α signalling pathways." (PMID 38169375, 2024). "As two isoforms of NAD(P)H oxidase, NOX2 and NOX4 are primary resources for ROSs in cardiovascular cells, and targeting NOX2 and/or NOX4 could be an important strategy for treating cardiovascular diseases." (PMID 37371773, 2023). "Indeed, the NOX4 accumulation contributes to the development of cardiovascular diseases by triggering an excessive ROS production." (PMID 36035984, 2022). "However, further studies discovered that NOX4 also has a detrimental effect in several animal models of cardiovascular disorders." (PMID 32664404, 2020). "However, compared to ECs from subjects who were more at risk for cardiovascular disease, ECs from subjects with lower risk exhibited a lesser amount of flow-induced NADPH oxidase 4 (NOX4)." (PMID 29127504, 2017). "Furthermore, dysregulation among genes including Nox4, Cx43, PGC1α, VEGFA, and TSP1 are reported with increased risk of cardiovascular diseases." (PMID 37493006, 2023). "Moreover, the downregulation of NOX4 expression induced by dihydrotanshinone I (a natural compound extensively used for treating cardiovascular diseases) may impede atherosclerotic plaque formation and reduce oxidative stress in atherosclerotic mice." (PMID 33744854, 2021). "Luteolin plays positive role against cardiovascular disorders by improving cardiac function, decreasing the release of inflammatory cytokines and cardiac enzymes, prevention of cardiac fibrosis and hypertrophy; enhances level of CTGF, TGFβ1, ANP, Nox2, Nox4 gene expressions." (PMID 39830909, 2025). "Previous studies denoted that the NOX1, NOX2, and NOX4 enzymes are expressed in cardiovascular tissues and not only participate in normal vascular and cardiac function but also contribute to the development of cardiovascular disease." (PMID 29156835, 2017).
infection (29 papers, 2010 to 2026). The state of being infected such as from the introduction of a foreign agent such as serum, vaccine, antigenic substance or organism. "Influenza A virus infection of NOX4 TG mice resulted in significantly less weight loss than that of WT mice at 3-days post infection." (PMID 35601109, 2022). "Although Nox4+/+ mice succumbed to the virulent RH strain from 9 d after i.p. injection, Nox4−/− mice were more susceptible to RH strain infection than Nox4+/+ mice." (PMID 28743960, 2017). "Treatment with NADPH oxidase inhibitor diphenyleneiodonium (DPI) and knocking down NOX4 expression with siRNA prevented viral replication in this in vitro model of infection." (PMID 35601109, 2022). "Expression of macrophage and neutrophil chemoattractants CXCL10, CCL3, CXCL1 and CXCL2 in the lung tissue were significantly lower in NOX4 TG mice compared to the WT mice at 3-days post infection." (PMID 35601109, 2022). "Whilst there was also a significant increase in ROS production to IAV infection in NOX4 TG mice at 3- and 7-days post infection, the magnitude of this response was significantly lower than that observed in WT mice." (PMID 35601109, 2022). "NOX4 mRNA expression in lung tissue of HK x-31-infected WT mice was significantly reduced at day 3 post infection and at 7-days post infection compared to the uninfected WT mice." (PMID 35601109, 2022). "Viral titres were decreased in infected NOX4 TG mice compared to the infected WT mice, at both 3- and 7-days post infection and there was significantly less lung alveolitis, peri-bronchial inflammation and neutrophil infiltration." (PMID 35601109, 2022). "Weight loss was one of the indicators of morbidity assessed in this study and while all mice lost weight when infected with HK x-31, the NOX4 TG mice lost less weight than infected WT mice at the earlier time point after infection." (PMID 35601109, 2022). "On the other hand, among the NADPH oxidase genes, only NOX4 was significantly reduced after infection with NOX5-β adenovirus." (PMID 33572841, 2021). "Another counter-argument against is a difference in the kinetics of accumulation of NOX1 and NOX4 in HCV-infected cells: NOX1 is accumulated shortly after the infection, whereas a pronounced increase in the expression of NOX4 occurs only after two weeks." (PMID 27965466, 2017). "After infection with T. gondii, a lower Ifngr1 mRNA and a higher expression of Tlr4 mRNA were observed in Nox4−/− BMDMs." (PMID 28743960, 2017). "In Aedes aegypti, infection with Micrococcus luteus or Wolbachia (wMel strain) also increases NOX4-art expression." (PMID 28356077, 2017). "The concentration of NOX4 in group A was similar on each day of the infection." (PMID 38041167, 2023). "Indeed, it was found that the expression of NOX4 was increased during cell infection, while inhibition of NOX4 activity blocked ROS increase, the phosphorylation of MAPK, the nuclear export of the vRNP and the viral release." (PMID 36298629, 2022). "Interestingly we observed a significant decrease in lung levels of IAV polymerase mRNA in NOX4 TG mouse lungs compared to the WT mice at both 3- and 7-days post infection suggesting endothelial NOX4 suppresses viral replication." (PMID 35601109, 2022). "However, the degree of neutrophil infiltration in infected NOX4 TG mice at 3- and 7-days post infection was significantly lower than in the WT mice." (PMID 35601109, 2022). "Interestingly, this protective effect of NOX4 overexpression in the lung endothelium appeared to occur mainly during the early phases of the infection." (PMID 35601109, 2022). "A similar mechanism could be responsible for the decrease in NOX4 and it is also important to consider that this expression may be variable over the course of the infection." (PMID 35601109, 2022).
infection (continued). "In contrast, whilst IAV infection increased BALF cell counts in the NOX4 TG mice compared to the NOX4 TG uninfected group, the magnitude was significantly smaller than that observed in the WT mice at both Day 3 post infection and Day 7 post infection." (PMID 35601109, 2022). "NOX4 TG mice had a modest but significant decrease in weight loss compared to the infected WT mice at day 2 and day 3 post infection, but not at day 7 post infection." (PMID 35601109, 2022). "In the present study, we found that Nox4-, but not Nox2- or p47phox-, deficient mice succumbed to infection with the highly virulent type I RH strain faster than WT mice and also failed to control the growth of the moderately virulent ME49 strain in the brain." (PMID 28743960, 2017). "In our system, we have checked the Nox4 expression level with RGNNV infection." (PMID 21991373, 2011). "We could detect Nox4 expression by intestinal epithelial cells which facilitated rapid ROI production upon infection and paracrine activation of neighbouring cells." (PMID 21124989, 2010). "Therefore, we measured the expression of NOX4 at 3- and 7-days post infection to determine whether IAV infections can alter the expression of NOX4 in vivo." (PMID 35601109, 2022). "Infection of hypoxia-reoxygenated GECs also resulted in significantly increased CEACAM6 and NOX4-mediated ROS generation compared to normoxic GECs." (PMID 40325849, 2025). "Upon infection, mitochondrial stress is increased and an imbalance occurs leading to the expression of mitochondrial NADPH oxidase 4 (NOX4)." (PMID 36361818, 2022). "Mice were culled at either 3 or 7 days post-infection to analyse: airway inflammation by bronchoalveolar lavage fluid (BALF) cell counts; NOX4, as well as inflammatory cytokine and chemokine gene expression by QPCR; and ROS production by an L-012-enhanced chemiluminescence assay." (PMID 35601109, 2022). "Infection of bone marrow-derived macrophages (BMDM) with S. aureus revealed that NADPH oxidase 2 (NOX2-) deficient, but not NOX1- or NOX4-deficient, BMDM failed to clear intracellular S. aureus." (PMID 33868252, 2021). "Infection of mouse lung with P. aeruginosa increased NOX4 expression in WT and Sphk1−/− mice; however, there was no robust increase in the expression of NOX4 in the lungs of Sphk2−/− mice exposed to P. aeruginosa." (PMID 33802941, 2021). "PA infection stimulates the human lung microvascular endothelial cells (HLMECs) towards apoptosis via activation of NOX4 but not NOX2, resulting in elevated lung permeability." (PMID 30050663, 2018). "Commonly, PA infection in the lungs leads to the activation of NOX2 and NOX4." (PMID 30050663, 2018). "Mechanistically, early infection transiently activated NRF2 via AKT-dependent inhibition of GSK3β, enhancing antioxidant defenses, but prolonged infection suppressed NRF2 activity due to AKT dephosphorylation and GSK3β activation, sustaining NOX4 upregulation and exacerbating oxidative stress." (PMID 41504438, 2026). "However, mutating Ncf4 and Nox4, two murine orthologs (pentagons) of the non-disease proteins (but PC members) NCF4 and NOX4, causes the phenotype Increased susceptibility to infection in mouse." (PMID 32591566, 2020). "Here, we demonstrate that during the acute phase of infection HCV replicates with a high rate, thus inducing intense apoptosis in infected cells; in this phase, a marked oxidative stress was registered mainly due to NOX4 activity and to a decrease of GSH and consequently of GSH/GSSG ratio." (PMID 30906503, 2019). "To demonstrate more specifically that the increased oxidative stress in the setting of β-arrestin-1 or -2 overexpression is due to increased Nox4 activity, we treated control CFs with apocynin, a non-specific Nox inhibitor, following infection with Ad-βarr1, Ad-βarr2 or Ad-Null." (PMID 26449263, 2015).